ICAM1 (intercellular adhesion molecule 1)
Diseases named in the same sentence as ICAM1 in open-access papers (continued):
Sharing a sentence is not in itself a finding about the gene and the disease.
breast carcinoma (191 papers, 2006 to 2025). "A lncRNA associated with breast cancer cells increased expression of ICAM1, which mediated vascular co-option by increasing tumor cells’ ability to stretch over brain capillaries and extravasate into the brain parenchyma." (PMID 40076927, 2025). "Les-6287 reduced the concentration of MMP-2, MMP-9, and ICAM-1, all of which are linked to metastasis and a poor prognosis in breast cancer patients." (PMID 39199694, 2024). "To evaluate the potential clinical association of ICAM-1 and uPAR in breast cancer patients, we first compared ICAM-1 and uPAR protein expression between different breast cancer subtypes using Clinical Proteomic Tumor Analysis Consortium (CPTAC) data sets." (PMID 37345070, 2023). "TAN cause breast cancer cells to migrate by activating intracellular adhesion molecule-1 (ICAM-1) on these cells." (PMID 37108425, 2023). "We also found that the frequency of ICAM1 mutation in breast cancer is about 2%, and the mutation is mainly in the form of amplification, accompanied by a point mutation and structural variation." (PMID 37671167, 2023). "Another article has reported that ICAM-1 expression by breast cancer tumors is associated with longer relapse-free periods and overall survival." (PMID 37237555, 2023). "ICAM1 contains 4 immunoglobulin domains, and the T231M mutation frequency is the highest in breast cancer (red arrows)." (PMID 37671167, 2023). "ICAM-1 on the human MDA-MB-231 breast cancer cell line was also implicated in circulating tumor cell (CTC) cluster formation, intravascular cell aggregation and increased metastatic potential." (PMID 35911772, 2022). "ICAM-1-deficient breast cancer cells developed, however, much larger metastatic lesions than their control counterparts." (PMID 35911772, 2022). "The analysis of breast cancer patient data suggests that the expression of ICAM-1 on breast tumor cells is associated with longer relapse-free periods and a higher overall survival of breast cancer patients." (PMID 35911772, 2022). "Specifically, it correlated the levels of four circulating inflammatory biomarkers (high-sensitivity C-reactive protein, fibrinogen, N-acetyl side-chains of acute phase proteins, and soluble intercellular adhesion molecule-1) with breast cancer risk." (PMID 33803201, 2021). "ICAM-1-ICAM-1 homophilic interaction was associated with breast cancer metastatic amplification, while ALCAM-ALCAM interaction was an assistant for T cell adhering to dendritic cells." (PMID 34222020, 2021). "It is in accordance with our finding that a previous research has also verified that ICAM-1 was implicated in Notch-1 signaling pathway in breast cancer." (PMID 31343412, 2019). "HRG enhanced the adhesion of MDA-MB-361 and SKBr3 cells to collagen I, concomitant with induction of ICAM-1, a β2-integrin receptor associated with enhanced invasion, motility and metastasis in breast cancer." (PMID 25668816, 2015). "Similar to our results, the ICAM-1 rs5498 SNP showed a statistical difference in susceptibility to prostate cancer, breast cancer, and grade II astrocytomas." (PMID 24069166, 2013). "In silico analysis confirmed higher numbers of tumour-infiltrating lymphocytes in basal breast cancers and that higher numbers were significantly associated with endothelial cell activation molecules, co-clustering with upregulated ICAM-1 and VCAM-1 amongst others." (PMID 39792888, 2025). "Numerous cancers, particularly breast cancer, have been linked to ICAM1 overexpression." (PMID 39755633, 2025). "This is supported by studies showing that the high densities of tumor-associated high endothelial venules expressing ICAM1 in breast cancer have been demonstrated to be correlated with the increase of T cell infiltration and cytotoxicity, as measured by flow cytometry and PCR analyses." (PMID 39093451, 2024).
breast carcinoma (continued). "Moreover, correlation analysis between ICAM1 and various tumor-infiltrating immune cells in different molecular subtypes of breast cancer demonstrated the strongest association between ICAM1 expression and neutrophil infiltration in TNBC." (PMID 38907234, 2024). "However, a recent study found that ICAM1-deficient breast cancer cells develop large metastatic lesions." (PMID 37671167, 2023). "The normal growth of ICAM-1-deficient breast cancer cells in primary tumors was associated with the normal tumor content of various CD45+ immune cells recruited by primary E0771 tumors with a small reduction in the DC and B-cell content in the draining LNs of the breast cancer tumors." (PMID 35911772, 2022). "Our current findings suggest for the first time that breast cancer–expressed ICAM-1 accounts for the susceptibility of breast cancer CTCs entrapped inside lung vessels to intravascular killing by these neutrophils, most probably as they circulate through these vessels." (PMID 35911772, 2022). "ICAM1, a cell surface protein which is directly involved in cellular transmigration, has been reported to be induced by ROS and is associated with increased invasiveness and metastasis of breast cancer cells." (PMID 30469399, 2018). "Therefore, we investigated the expression of a panel of different genes that have previously been implicated either in LFA-1/ICAM-1 signalling in other tumour types or in metastatic spread of breast cancer." (PMID 27447568, 2016). "Indeed, we found that some ICAM-1+ CTCs were associated with neutrophils in breast cancer patients, suggesting that ICAM-1 on tumor cells may directly mediate tumor cells binding with neutrophils." (PMID 37345070, 2023). "Notably, ICAM-1 overexpression has been associated with more aggressive tumor phenotypes and poor prognosis in different types of malignancies, including multiple myeloma, breast cancer, gastric cancer, liver cancer, and pancreatic cancer." (PMID 29228586, 2017). "ICAM-1 expressed by metastatic breast cancer cells that expand inside the lung vasculature is involved in innate rather than in adaptive cancer cell killing, functioning as a suppressor of intravascular breast cancer metastasis to lungs." (PMID 40475782, 2025). "Lastly, monocytes isolated from individuals with early-stage breast cancer show decreased expression of key markers, including intercellular adhesion molecule 1 (ICAM-1; encoded by ICAM1), CD80 & CD86, and lower levels of TNF-α." (PMID 41550427, 2025). "Numerous studies have confirmed that ICAM1, as an oncogene, plays a key role in pathological processes of various types of tumors, including colorectal and breast cancer." (PMID 40838069, 2025). "Heregulin also upregulates intercellular adhesion molecule 1 (ICAM1), which is linked to increased invasion, motility, and metastasis in breast cancer." (PMID 40076927, 2025). "There was evidence that TNBCs had higher levels of ICAM1 mRNA and proteins when compared to normal breast tissues and other subtypes of breast cancer." (PMID 39755633, 2025). "Meanwhile, basic research has shown that neutrophils can promote breast cancer progression by adhering to TNBC cells via CD11b‐ICAM1." (PMID 41310989, 2025). "Elevated ICAM-1 expression in breast cancer cells results in a favorable outcome and prolonged survival of breast cancer patients." (PMID 40475782, 2025). "The assessment of ICAM-1 expression in different subtypes of breast cancer was thus conducted by validation utilizing two datasets: GSE45827 and GSE36693." (PMID 38799250, 2024). "In an in vivo breast cancer mouse model, atorvastatin intervention significantly reduced ICAM1 expression on tumor cells, attenuated TINs infiltration, and downregulated the MAPK signaling pathway." (PMID 38907234, 2024).
breast carcinoma (continued). "Analysis of the TCGA database revealed greater ICAM1 expression in breast cancer tissues than in normal breast tissue, with triple-negative breast cancer exhibiting the highest ICAM1 expression among all breast cancer subtypes." (PMID 38907234, 2024). "ICAM-1 expression is usually increased in more aggressive cancers, including triple-negative-subtype breast cancer and non-small cell lung carcinoma." (PMID 39199664, 2024). "This study found that ICAM-1 was raised in several malignancies, including breast cancer, and considerably overexpressed in TNBC." (PMID 38799250, 2024). "Our initial analysis of ICAM-1 expression in many cancers using the TCGA database revealed that it was substantially expressed in a range of malignancies, including breast cancer." (PMID 38799250, 2024). "FKA demonstrates effective inhibition of VEGF, GLUT1, and ICAM-1 expression in the mammary carcinoma, resulting in a significant suppression of new vascular formation." (PMID 38611849, 2024). "In our study, we confirmed the inhibitory effect of Les-6287 on the ICAM-1 concentration in the MDA-MB-231 breast cancer cell line belonging to TNBC." (PMID 39199694, 2024). "On the other hand, ICAM-1’s function in tumor inflammatory response and metabolism emerged after breast cancer was reclassified as TNBC." (PMID 38799250, 2024). "The results obtained at the ELISA measurements proved that the Les-6287 compound can decrease the concentration of MMP-2, MMP-9, and ICAM-1 proteins involved in metastasis and poor prognosis in breast cancer patients." (PMID 39199694, 2024). "In breast cancer's tissues and cells, ICAM-1 exhibited declined levels as compared to normal breast epithelia or benign breast cells." (PMID 39050471, 2024). "This study explored the role of ICAM-1 in breast cancer and its triple-negative subtypes by systematic bioinformatics methods." (PMID 38799250, 2024). "We found that the MMP-9 and ICAM-1 concentrations in MCF-7 breast cancer cells were below the detection range." (PMID 39199694, 2024). "Compared to normal tissues, breast cancer tissues exhibited a considerably greater average expression level of ICAM-1 mRNA (p < 0.001)." (PMID 38799250, 2024). "The mRNA expression pattern of ICAM-1 in breast cancer tissues and normal tissues was discovered using TCGA databases." (PMID 38799250, 2024). "The results showed that the expression of ICAM-1 in breast cancer tissues was significantly higher than that in normal tissues, especially in TNBC subtypes." (PMID 38799250, 2024). "In conclusion, breast cancer is characterized by significantly high expression of ICAM-1, with TNBC subtypes expressing ICAM-1 at much higher levels than other subtypes." (PMID 38799250, 2024). "In summary, ICAM-1 is differentially expressed in a variety of tumors, with a notable upregulation in breast cancer, particularly triple negative breast cancer." (PMID 38799250, 2024). "To investigate ICAM-1 expression in breast cancer further, we obtained tissue samples from TNBC patients and categorized them for immunohistochemistry." (PMID 38799250, 2024). "ICAM1 overexpression in lung and breast cancer promotes spontaneous metastasis to the lung and is associated with shorter survival in breast cancer." (PMID 37874534, 2024). "In breast cancer, ICAM-1 mainly activates pathways related to apoptosis and epithelial–mesenchymal transition, while its overexpression in TNBC is associated with inflammatory response, apoptosis, and other processes." (PMID 38799250, 2024). "There were 76 proteins detected only in the AQP1-overexpressing group, including proteins reported to exert prosurvival and/or prometastatic activities in breast cancer, such as intercellular adhesion molecule 1 (ICAM1), cathepsin S (CTSS), and PLAT." (PMID 36803413, 2023). "In the current study, we observed a significant correlation between parameters of psychosocial stress and ICAM-1 in breast cancer survivors on AIs." (PMID 36717689, 2023).
breast carcinoma (continued). "ICAM-1 expression is reportedly elevated in breast cancer cells compared with the surrounding healthy tissue and is expressed especially highly in triple-negative breast cancer tumors." (PMID 37237555, 2023). "Promoter study of ICAM1 gene in GD3 synthase overexpressed condition showed a supressed transcriptional activity in ER-breast cancer cell lines." (PMID 38089042, 2023). "TAN also show the expression of β2-integrins, which involves the direct interaction of neutrophils with breast cancer cells and the interaction of β2-integrins with ICAM-1 on the cancer cell." (PMID 37108425, 2023). "Treating breast cancer cells with gossypol has been shown to block the binding of NF-κB to the promoter regions of ICAM-1, suppressing TNF-α-induced ICAM-1 expression." (PMID 38098026, 2023). "GROα, ICAM 1 and Cox-2 are SASP factors that are also closely associated with the progression and metastasis of breast cancer." (PMID 36982207, 2023). "Knockdown of ICAM-1 in breast cancer cells in vitro has been shown to decrease the expression of genes related to stemness, to decrease invasion of cells through Matrigel, and to decrease transendothelial migration across HUVEC monolayers." (PMID 37237555, 2023). "Consistent with mouse studies, ICAM-1 gene expression was also positively correlated with PLAUR gene expression in TCGA breast cancer data sets (p < 0.05)." (PMID 37345070, 2023). "In another study, ICAM-1-positive breast cancer cells were able to use neutrophil granulocytes as a linker to indirectly attach to endothelial cells in vitro." (PMID 37237555, 2023). "Correlation analysis using 194 IDC patients or the GEPIA database indicated that AQP1 was positively correlated with ANXA2, Rab1b, CTSS, and ICAM1 in breast cancer patients." (PMID 36803413, 2023). "Collectively, our results are a first indication that ICAM-1 expressed by metastatic breast cancer cells that expand inside the lung vasculature is involved in innate rather than in adaptive cancer cell killing." (PMID 35911772, 2022). "In some settings, neutrophil–cancer cell interactions mediated by neutrophil LFA-1 and cancer ICAM-1 were shown to facilitate breast cancer metastasis." (PMID 35911772, 2022). "Our results therefore elude to a novel contribution of ICAM-1 to breast cancer cell killing by neutrophils inside the lung vasculature." (PMID 35911772, 2022). "Nevertheless, the in vivo roles of ICAM-1 in breast cancer cell growth and metastasis are still poorly understood." (PMID 35911772, 2022). "Previous research also found that ICAM-1 promotes CTCs adhesion to pulmonary microvessels and transendothelial migration in breast cancer pulmonary metastasis." (PMID 36160416, 2022). "In the group of patients following breast cancer treatment, the serum levels of ICAM-1 and PECAM-1 were 555 and 98 ng/mL, respectively." (PMID 35366289, 2022). "As a downstream factor of extracellular signal-related kinase, ICAM-1 plays a role in regulating the metastasis of human breast cancer cells." (PMID 35565262, 2022). "In an intergroup comparison, patients after breast cancer treatment showed a statistically significant increase in the level of ICAM-1 and PECAM-1 molecules." (PMID 35366289, 2022). "ICAM1, ICAM4, and ICAM5 are associated with breast cancer susceptibility loci as indicators of disease severity." (PMID 35341150, 2022). "Collectively, our results suggest that TENs use ICAM-1 expression on E0771 cells entrapped inside the lung vasculature to eliminate intravascular metastatic breast cancer cells before they can expand into metastatic lesions." (PMID 35911772, 2022). "We next tested if ICAM-1 expression by E0771 cells affects the intrinsic growth of these breast cancer cells." (PMID 35911772, 2022). "Here, the authors show that ICAM1 is enriched in CTC clusters and its loss suppresses cell-cell interaction and CTC cluster formation, and propose ICAM1 as a therapeutic target for treating breast cancer metastasis." (PMID 34381029, 2021).
breast carcinoma (continued). "Meta-analysis of various breast cancer gene expression datasets using bc-GenExMiner and the TCGA database further demonstrated a significant positive correlation between ICAM1 with CDK6 mRNA levels." (PMID 34381029, 2021). "ICAM1, which is a hub protein for lymphoma trafficking, has been shown to be overrepresented in several carcinomas, including breast carcinoma." (PMID 33562532, 2021). "To do so, we first used a fluorescently labeled the ICAM-1 antibody to verify the antigen expression on a few selected breast cancer cell lines and normal cells." (PMID 35056985, 2021). "Next, we examined the role of ICAM1-induced molecular alterations of breast cancer cells in metastasis." (PMID 34381029, 2021). "(Harvard Dataverse): The potential of lunasin extract for the prevention of breast cancer progression by upregulating E-Cadherin and inhibiting ICAM-1." (PMID 34691393, 2021). "We next investigated the effects of LFA1-P on GT DcNPs ability to inhibit ICAM-1-expressed breast cancer cell growth." (PMID 35056985, 2021). "A previous study has shown that lung metastatic breast cancer cells aberrantly expressed ICAM-1- and VCAM-1-promoted metastatic cells for survival in the parenchyma microenvironment of lung." (PMID 34760697, 2021). "The cellular potency of the GT DcNP, the GT DcNP-LFA1-P (1%), the GT DcNP-LFA1-P (2%), and the GT-free drug combination were tested in 4T1 breast cancer cells, expressing ICAM-1." (PMID 35056985, 2021). "Neutrophil interaction with ICAM-1 on the human breast cancer cell MDA-MB-468 enhanced the migratory activity of the tumor cells." (PMID 34572138, 2021). "Based on the flow profiles of 30 blood samples collected from advanced breast cancer patients at Northwestern University in a prospective study, we found that ICAM1 expression was significantly enriched in CTC clusters compared to that of single CTCs." (PMID 34381029, 2021). "ICAM-1 and E-Cadherin, molecules involved in breast cancer adhesion and progression, were evaluated in each group to determine their effect." (PMID 34691393, 2021). "Among the four tested, the mouse 4T1 and human MDA-MB-231 breast cancer cells exhibited significant cell surface ICAM-1 expression as evident in a high degree of antibody fluorescence." (PMID 35056985, 2021). "Consistent with this, the expression of ICAM-1 is negatively correlated with the incidence of lymph node or distant metastasis in patients with breast cancer and colorectal cancer, suggesting a favorable prognosis." (PMID 34249711, 2021). "MUC1 protein can attach to intercellular adhesion molecule-1 (ICAM-1), which promotes breast cancer cells adhesion to endothelial cells, leading to adhesion and consequent migration through the vessel wall." (PMID 34681197, 2021). "(Harvard Dataverse): ARRIVE checklist for “The potential of lunasin extract for the prevention of breast cancer progression by upregulating E-Cadherin and inhibiting ICAM-1”." (PMID 34691393, 2021). "In the breast cancer model, results revealed an inverse correlation between ICAM-1 and E-Cadherin expressions." (PMID 34691393, 2021). "By examining the effects of LE on these two molecules, this study is expected to investigate the potential of LE for the prevention of breast cancer progression via ICAM-1 and E-Cadherin expression pathway." (PMID 34691393, 2021). "Stimulation with recombinant human IL-8 increased mucin-1 in MCF-7 and T47D breast cancer cells and decreased intercellular adhesion molecule 1 (ICAM-1) as well as vascular cell adhesion molecule 1 (VCAM-1) in T47D cells." (PMID 33809315, 2021). "To evaluate the potential of the tumor antigen ICAM1 as an immunotherapeutic target, we performed IHC staining to detect ICAM1 protein expression in breast cancer tissue microarrays." (PMID 33072116, 2020). "FBXO4 also shows tumor suppressive functions in breast cancer and lung cancer through ubiquitin dependent degradation of intercellular adhesion molecule 1 (ICAM1) 136 and MCL1 137 respectively." (PMID 32226545, 2020).